SNORD113-2 (small nucleolar RNA, C/D box 113-2)
Synonyms: 14q(I-2)
Gene: Small nucleolar RNA gene on chromosome 14 (100,927,342 to 100,927,413, forward strand). Ensembl gene ENSG00000212384.
Homologues: Orthologues: chimpanzee SNORD113-2 (100% identical). Paralogues in human: SNORD113-3 (76% identical), SNORD113-8 (71% identical), SNORD113-9 (68% identical), SNORD113-7 (67% identical), SNORD113-5 (65% identical), SNORD113-6 (65% identical), SNORD114-10 (65% identical), SNORD113-4 (62% identical), SNORD114-4 (60% identical), SNORD114-12 (58% identical), SNORD114-18 (58% identical), SNORD114-2 (58% identical), and 26 more.